RN7SL178P (RNA, 7SL, cytoplasmic 178, pseudogene)
Gene: Miscellaneous RNA gene on chromosome 8 (8,582,352 to 8,582,655, reverse strand). Ensembl gene ENSG00000263616.
Homologues: Orthologues: chimpanzee Metazoa_SRP (99% identical), macaque Metazoa_SRP (91% identical). Paralogues in human: RN7SL2 (85% identical), RN7SL1 (84% identical), RN7SL3 (83% identical), RN7SL507P (80% identical), RN7SL218P (79% identical), RN7SL45P (79% identical), RN7SL126P (79% identical), RN7SL444P (79% identical), RN7SL47P (79% identical), RN7SL11P (78% identical), RN7SL230P (78% identical), RN7SL448P (78% identical), and 700 more.